MIR939 (microRNA 939)
Synonyms: hsa-mir-939; MIRN939; mir-939
Gene: MicroRNA gene on chromosome 8 (144,394,149 to 144,394,230, reverse strand). Ensembl gene ENSG00000284310.
Gene Ontology:
Biological process: miRNA-mediated post-transcriptional gene silencing
Cellular component: RISC complex
Homologues: Orthologues: chimpanzee ptr-mir-939 (100% identical), macaque mml-mir-939 (99% identical).